PPARG (peroxisome proliferator activated receptor gamma)
Diseases named in the same sentence as PPARG in open-access papers (continued):
Sharing a sentence is not in itself a finding about the gene and the disease.
depression (61 papers, 2015 to 2026). "Together, these findings demonstrate that the loss of PPARγ in D2-MSNs leads to depression-like phenotypes, underscoring the critical role of PPARγ in maintaining emotional homeostasis." (PMID 41510157, 2026). "The dysfunction of PPARγ is accompanied by mental illness, which is a genetic risk factor for depression." (PMID 38822367, 2024). "PGC1α has been linked with depression and bipolar disorders, and its target, PPARγ, provides a plausible link between MeS and behavior." (PMID 36224260, 2022). "Growing evidence suggests that the downregulation of PPARγ is tightly associated with a high risk for depression development." (PMID 26398946, 2015). "Our results indicate that seipin deficiency, by reducing the level of PPARγ, suppresses the proliferation of stem cells and neuronal differentiation of progenitor cells, causing depression-like phenotype." (PMID 26398946, 2015). "Apart from metabolic effects, PPARG has been implicated in anxiety and depression regulation." (PMID 40766923, 2025). "Further studies revealed that duloxetine upregulated the protein expression of PPARγ in the prefrontal cortex and hippocampus, indicating its potential to suppress neuroinflammation associated with depression by inhibiting the transcription of proinflammatory genes through PPARγ." (PMID 38877455, 2024). "Finally, I will provide an overview of the biological changes associated with depression, with particular emphasis on the extensive roles of the PPARg system in depressive illness." (PMID 34502154, 2021). "PPARγ mediates the microglia activation phenotype, which may be related to the susceptibility of stressed ob/ob mice to depression." (PMID 34869441, 2021). "Furthermore, decreased expression of PPARγ in neuronal cells of young mice has been associated with spatial cognitive deficits, anxiety‐ and depression‐like behaviors, and neuro‐inflammatory effects, which can be reversed by Rosi." (PMID 33219735, 2020). "The insights gleaned from our research highlight the therapeutic potential of PPARγ in the brain as a therapeutic target for the treatment of depression, particularly those impacting specific neuronal subtypes." (PMID 41510157, 2026). "Peroxisome proliferator-activated receptor gamma (PPARγ) plays an important role in modulating the pathophysiology of depression." (PMID 41510157, 2026). "A gap in our understanding remains regarding how GlcCer-PPARγ signaling in D2-MSNs regulates depression-like behaviors." (PMID 41510157, 2026). "Among transcription factors, peroxisome proliferator-activated receptor gamma (PPARγ), a ligand-activated nuclear transcription factor, has been shown to be an important player in modulating the pathophysiology of depression." (PMID 41510157, 2026). "Administration of GlcCer or the PPARγ agonist pioglitazone reverses stress-induced depression-like behaviors, combined GlcCer and pioglitazone exerts additive antidepressant effects." (PMID 41510157, 2026). "Together, these findings demonstrate that maintaining PPARγ activity in the dorsal striatum is essential for alleviating depression-like behaviors." (PMID 41510157, 2026). "Collectively, these findings indicate that the reduction in PPARγ activity in D2-MSNs is a major contributor to depression-like behaviors in D2-Ugcgf/f mice." (PMID 41510157, 2026). "Some research show that the overexpression of PPARγ in hippocampus protects mice against depression like behaviors induced by chronic stress." (PMID 40371339, 2025). "To summarise, the present study further supports that LPS-activated inflammasomes accelerate neuroinflammation and lead to depression by triggering PPARγ/CX3CR1/Nrf2 and the NF-κB/NLRP3 signaling pathways." (PMID 40308754, 2025). "The augmentation of PPARγ can have a positive impact on various important pathological processes of depression." (PMID 40371339, 2025). "It should be noticed that in addition to PPARα, PPARδ and PPARγ have been reported to correlate with depression as well." (PMID 40356991, 2025).
depression (continued). "Our study indicates that the inhibition of PPARγ leads to a suppression of IL-10 expression in microglia during depression." (PMID 38822367, 2024). "Previous reports have demonstrated that neuronal PPARγ directly mediated stress-induced emotional disorders and PPARγ agonists have an antidepressant effect, suggesting the essential role of PPARγ in depression." (PMID 38822367, 2024). "It is important to note that PPARG and PPARA are involved in lipid and glucose metabolism, while CHRM2 has been linked with depressive disorder." (PMID 37106802, 2023). "Now, many PPARγ agonists to address major depressive disorder, have tested in a few clinical trials." (PMID 36142731, 2022). "Long-term treatment with PPARγ agonist can relieve anxiety- and depression-like symptoms through decreasing the expression of inflammatory gene programs." (PMID 35098831, 2022). "PPARg agonists are potent stimuli to both neuroplasticity and neurogenesis, which, I will show, are both markedly decreased in depression." (PMID 34502154, 2021). "This roles of stress system dysregulation in depression and of the PPARg’s role in regulating the stress system response and its dysregulation in depression are extremely important, and hence will be the highlights of this publication." (PMID 34502154, 2021). "PPARg agonists have activity on a striking multiplicity of interrelated pathophysiological CNS processes we now know occur in patients with major depression." (PMID 34502154, 2021). "EPA and DHA can act as natural ligands of peroxisome proliferator-activated receptor γ (PPARγ) and inhibit the neuronal para-inflammatory cascade in the pathophysiological process of depression." (PMID 34531367, 2021). "In summary, PPARg augmentation can impact positively on multiple significant pathological processes in depression." (PMID 34502154, 2021). "Our results were consistent with previous studies that PPARG plays a crucial role in regulating depression and depressive behaviors." (PMID 33968145, 2021). "PPARγ agonists, also named thiazolidinediones, have been relatively well investigated and supported as potential candidates for the treatment of depression." (PMID 32971941, 2020). "Existing clinical studies that explore the effects of PPARγ agonists on major depressive disorder and bipolar depression mainly suffer from small sample size." (PMID 31614690, 2019). "PPARγ agonists to address mood disorders, especially major depressive disorder and depressive episodes in bipolar disorder, have been tested in a few clinical trials." (PMID 31614690, 2019). "It was demonstrated that the PPARγ agonist pioglitazone (2.5 mg/kg) ameliorated depression-like behaviors in CMS-treated mice, as indicated by body weight (BW), the SP test, the FST, and the TST." (PMID 27716270, 2016). "Peroxisome proliferator-activated receptor γ (PPARγ) is a nuclear receptor regulating inflammation and microglial polarization and, therefore, a potential target for resolving depressive disorders." (PMID 27716270, 2016). "Furthermore, given the neuronal heterogeneity and complexity of brain regions 17, 18, unraveling how PPARγ signaling pathways function within specific neuronal subtypes is crucial for the precise development of PPARγ-targeted therapies for depression." (PMID 41510157, 2026). "GlcCer-PPARγ signaling exerts antidepressant-like effects, which are further enhanced by pioglitazone co-treatment, highlighting a promising therapeutic strategy for depression by targeting GlcCer-PPARγ signaling." (PMID 41510157, 2026). "As in the case of psoriasis, inhibiting the CD19 expression caused an increase in the concentration of PPARγ, Wnt3a, and β-catenin; therefore, it is probable that CD19 regulates the symptoms of psoriasis and depression through the PPARγ/β-catenin/Wnt3a signaling pathway." (PMID 40141110, 2025).
depression (continued). "Recently, study has reported that by activating PPARγ, chronic mild stress-induced inflammatory response in microglia could be blocked and the depression- and anxiety-like behaviors can be ultimately improved." (PMID 39247617, 2024). "Besides, these fatty acids act as natural ligands of peroxisome proliferator-activated receptor gamma, downregulating the neuronal inflammatory cascade in the pathophysiological process of depression." (PMID 37353584, 2023). "Research has indicated that the PPARG agonist pioglitazone may have the potential to decrease the severity of depression." (PMID 38004472, 2023). "Notably, many studies found that activation of PPARγ improves mood disorders, especially in major depressive disorder and bipolar disorder." (PMID 36142731, 2022). "Many studies have demonstrated that PPARγ is an important therapeutic target for depression." (PMID 36142731, 2022). "Consistent with our hypothesis, GRb1 could upregulate PPARγ expression, and as a result, attenuated hippocampal neurogenesis abnormalities and improved depressive-like behaviors in mice model of depression." (PMID 34372875, 2021). "As in depression, PPARγ plays an important role in the pathogenesis of schizophrenia." (PMID 34072914, 2021). "In rodents, it has been demonstrated that PPARγ-agonists reduce depression-like behavior." (PMID 31319604, 2019). "A more recent study has shown that pioglitazone, a highly selective agonist for peroxisome proliferator-activated receptor γ (PPARγ), exerts an antidepressant-like activity through PPARγ-mediated amelioration of M1/M2 microglial imbalance in chronic mild stress-induced depression-like model mice." (PMID 28468634, 2017). "Based on the effects of PPARγ on the anti-inflammatory response, in this study we evaluated the antidepressant-like effects of the PPARγ agonist pioglitazone in CMS-induced depression using a mouse model and analyzed the role of M2 microglia in the antidepressant activity of pioglitazone." (PMID 27716270, 2016). "The peroxisome proliferator-activated receptor (PPARγ), participating in the regulation of amino acids, and glucose and lipid metabolisms, and in terminal keratinocyte differentiation, is down-regulated in patients suffering from psoriasis, as well as in patients with depression." (PMID 40141110, 2025). "Therefore, we reviewed studies on the interaction of CBD and PPARγ in depression." (PMID 39657242, 2025). "It has been reported that AS-IV may alleviate peroxisome proliferator-activated receptor γ (PPARγ)/ axis-mediated neuroinflammation and relieve depression-like behaviors in chronic restraint stress-induced and LPS-induced mice by up-regulating PPARγ expression." (PMID 40336842, 2025). "The improvement in depression correlated with normalization of pro-inflammatory biomarkers, including pro-inflammatory adipokines (leptin) or cytokine (IL-6), suggests a role for inflammatory pathways and intriguing links between PPARγ activation, depression, and inflammation." (PMID 32971941, 2020). "In light of the anti-inflammatory and neuroprotective activities of the PPARγ-dependent signaling pathway, we investigated the antidepressant effects of pioglitazone in a CMS mice model of depression." (PMID 27716270, 2016). "As expected, microinfusion of GlcCer failed to alleviate depression-like behaviors in D2-Ppargf/f mice, further supporting the requirement of functional PPARγ signaling for GlcCer-induced antidepressant effects." (PMID 41510157, 2026). "Establishing PPARγ AF1-dependent activation as a novel approach could open new avenues for the development of novel and more targeted therapeutics for depression." (PMID 41510157, 2026). "PPARγ agonist pioglitazone showed tremendous promises in many non-metabolic disorders like chronic kidney disease, depression, inflammation, and autoimmune diseases." (PMID 31614690, 2019).
depression (continued). "Furthermore, the NF-α1/CPE promoter contains a peroxisome proliferator-activated receptor (PPARγ) binding site which can be activated by rosiglitazone, a PPARγ agonist, to up-regulate expression of NF-α1/CPE and neurogenesis, resulting in anti-depression in animal models." (PMID 35711734, 2022).
heart failure (61 papers, 2009 to 2025). Inability of the heart to pump blood at an adequate rate to meet tissue metabolic requirements. "Specific drugs acting as PPAR agonists, such as Thiazolidinediones (TZDs), a class of PPARγ agonists, have been associated with fluid retention and heart failure." (PMID 39065726, 2024). "Although full PPARγ agonists profoundly improve blood glucose levels, TZDs are associated with increased edema and heart failure." (PMID 37190025, 2023). "The clinical controversy of rosiglitazone as a hypoglycemic agent is potentially associated with heart failure, mainly due to its potent activation of peroxisome proliferator-activated receptor γ (PPARγ)." (PMID 34305596, 2021). "In the past, pharmacological activation of PPAR (especially PPARγ) was reported to negatively modify cardiovascular risk and morbidity in heart failure patients." (PMID 34884498, 2021). "Several side effects of TZDs such as weight gain, fluid retention, and increased risk of heart failure seem to be PPARγ mediated." (PMID 29203903, 2017). "However, studies indicate that partial PPARγ agonists have lower risks of causing side effects (e.g., edema, fractures, and heart failure) relative to full PPARγ agonists, although they exhibit similar effects associated with insulin sensitivity." (PMID 30627576, 2018). "However, there are safety concerns: side effects, including dose limited side effects linked to PPARγ drug treatments, increased the risk of cardiac failure and potential carcinogenicity in rodents." (PMID 28415688, 2017). "In recent years, synthetic PPARγ partial agonists have emerged as a promising alternative to full agonists, demonstrating hypoglycemic efficacy while mitigating the risk of severe side effects commonly associated with full agonists, including weight gain, fluid retention and heart failure." (PMID 39459249, 2024). "As a positive regulator of peroxisome proliferator-activated receptor gamma (PPARγ), MTMR7 has certain diagnostic and therapeutic value for the prevention and treatment of heart failure." (PMID 38529329, 2024). "PPARγ activation prevents cardiac insufficiency by inhibiting apoptosis and necrosis, and by regulating PPARγ expression, it induces Bcl-2, Bax, and cytochrome-c expression changes and attenuates cardiomyocyte apoptosis." (PMID 36420656, 2022). "CR reduced cardiac PPARγ levels, concomitantly attenuating cardiac lipotoxicity which is one of the mechanisms responsible for diabetic cardiomyopathy and heart failure." (PMID 30071860, 2018). "Activation of PPARγ pathway has been shown to enhance fatty acid oxidation, improve endothelial cell function, and decrease myocardial fibrosis in heart failure." (PMID 27937122, 2017). "The newly identified natural products with PPARγ agonistic potency are considered as promising lead scaffolds to develop novel chemical therapeutics for heart failure." (PMID 27937122, 2017). "Patients with congestive heart failure are prone to develop heart failure following PPARγ therapy as a result of increased plasma volume." (PMID 28243251, 2017). "Level of expression of the PPARγ in the left ventricle sensitivity in detecting heart failure was 58% and its specificity was 92.9% (AUC 0.540, 95% CI 0.452–0.626; p = ns)." (PMID 25371662, 2014). "Level of expression of the PPARγ in the left ventricle sensitivity in detecting heart failure was 58% and its specificity was 92.9%." (PMID 25371662, 2014). "Our study in the normoglycemic heart failure model indicates that exosome stimulation through an increase in circulating adiponectin level should be one of the key mechanisms of such action of PPARγ agonists and provide the future opportunity of advanced therapeutic applications." (PMID 32652045, 2020). "It is worth noting that the direct effect of PPARγ on the heart leads to heart failure." (PMID 28243251, 2017).
heart failure (continued). "However, in the group of patients, in whom heart failure develops during the follow-up, higher myocardial PPARγ level seems to preserve the systolic function of the left ventricle." (PMID 29093735, 2017). "Nevertheless, heart failure, massive weight gain, and appearance of oedema are relevant to PPARγ." (PMID 28464894, 2017). "However, several clinical trials with these PPARγ agonists, such as rosiglitazone, have demonstrated that they may increase heart failure." (PMID 38719955, 2024). "While the primary indications for PPARγ agonist therapy focus on hyperlipidemia and diabetes, there is a growing body of preclinical data that suggests they may be beneficial in the treatment of heart failure." (PMID 27937122, 2017). "However higher levels of PPARγ gene transcript in the myocardium of patients who develop heart failure following CABG may have some protecting effect on cardiac contractility, which seem not to be directly related to exercise capacity." (PMID 29093735, 2017). "While PPARγ has been studied previously, from the clinical perspective PPARγ agonist might not be the best therapeutic agent due to the risk of developing heart failure." (PMID 27611931, 2016). "PPARγ and other PPAR agonists have various systemic adverse effects on heart failure, tumorigenesis, myalgia, and hepatic events, but they can hopefully be used to develop a safe drug for the treatment of fibrotic strictures." (PMID 39451206, 2024). "Moreover, previous studies demonstrated that SV ameliorated heart failure and other cardiovascular events by activating Peroxisome-proliferator-activated receptor gamma (PPARγ)-dependent pathways, and modulation of PPARγ signals helps provide pleiotropic protection of SV." (PMID 36902342, 2023). "During heart failure development, Apo F increased in an attempt to protect the myocardium by activating LXR/RXR signaling through CD36 and PPARγ activation." (PMID 30132266, 2018). "Aleglitazar from Roche, a Peroxisome proliferator-activated receptor gamma (PPARG) agonist, was terminated in phase III clinical trial in 2013 due to safety concerns for bone fractures, heart failure and gastrointestinal bleeding." (PMID 25946000, 2015). "The level of PPARγ in the myocardium was not able to predict development of heart failure after CABG, as was shown in our previous work." (PMID 29093735, 2017). "Since a reduced FA oxidation capacity causes energy starvation in a failing heart, modulating the technology of TEFA transport via several possible pathways, including PPARγ, Notch, and Meox2/TCF15, might open a new avenue to developing therapeutic strategies for energy-starved heart failure." (PMID 34940647, 2021). "Previous studies found that QL improved cardiac metabolism and mitochondrial function in heart failure induced by pressure overload, while QL also enhanced the metabolism of H9C2 cardiomyocytes by regulating peroxisome proliferator-activated receptor gamma (PPARγ) coactivator-1α (PGC-1α) expression." (PMID 32626732, 2020). "We found negative correlation between myocardial PPARγ expression and IL-6 level only before CABG, when none of patients had features of heart failure." (PMID 29093735, 2017).